CD2 (CD2 molecule)
Diseases named in the same sentence as CD2 in open-access papers (continued):
Sharing a sentence is not in itself a finding about the gene and the disease.
breast carcinoma (17 papers, 2017 to 2025). "Collectively, these findings demonstrate that CD2‐deficient CTLs promote breast cancer progression and brain metastasis by disrupting CD2–CD58 interactions." (PMID 40859981, 2025). "Overall, the decrease in expression of basal genes in Cd2+- transformed MCF-10A cells identify a set of genes associated with the outcome of breast cancer patients." (PMID 33062196, 2020). "However, in breast cancer, high CD2 expression is associated with a longer survival time." (PMID 35602471, 2022). "A study focused on the CD2 gene of breast cancer revealed that patients with high immune scores had improved OS, proving that the immune component of the immune microenvironment is a potential favorable factor in terms of the prognosis of BRCA patients." (PMID 38862250, 2024). "CD2, which is regarded as an immune response molecule, has been documented to be involved in breast cancer recurrence and metastasis and to play a vital role as a prognostic factor for patients with breast cancer." (PMID 32352014, 2020). "Here, our findings demonstrate for the first time the prognostic significance of MMP11 and CD2 expression in HR−/HER2+ breast cancer and suggest that they are promising biomarkers or drug targets for this subtype of breast cancer." (PMID 28409241, 2017). "This recent finding raises the possibility that the correlation between high CD2 expression and favorable prognosis of patients with HR−/HER2+ breast cancer in our study is related to the augmentation of NK cytotoxic activity against cancer cells by CD2." (PMID 28409241, 2017). "A new prognostic model for HR−/HER2+ breast cancer based on the expression of MMP11 and CD2 was developed and the DMFS for patients in the high-risk group according to our model was significantly lower than that for those in the low-risk group." (PMID 28409241, 2017). "In HR−/HER2+ breast cancer, MMP11 and three i-genes (BTN3A2, CD2, and TRBC1) were significantly associated with clinical outcomes, whereas no clinical variable was significant." (PMID 28409241, 2017). "Furthermore, the findings establish a theoretical foundation for considering CD2 as a potential biomarker and therapeutic target in breast cancer brain metastasis immunotherapy." (PMID 40859981, 2025). "Chen’s team found that CD2 was upregulated in breast cancer samples and that CD2 immunomodulation contributed to the mitigation of disease progression and could be used as an immunomodulatory agent in clinical treatment." (PMID 36591509, 2022). "In addition, tumor sphere formation and expression of breast stem cell marker genes such as CD44/CD2 were greatly inhibited by CSNK1G2 knockdown in ER+ breast cancer cells." (PMID 33861751, 2021). "However, this relationship was not assessed in this study, and further studies designed to unravel the association between CD2 expression and anti-HER2 antibody response or the value of CD2 in predicting anti-HER2 antibody response in HER2+ breast cancer will be required." (PMID 28409241, 2017). "As sgRNAs were unavailable for CD2, we alternatively knocked out CD58, the cognate ligand for CD2, in MDA-MB-231 breast cancer cells." (PMID 40955669, 2025). "Then based on the median expression levels of CD2, ZNF683 and KLRB1 separately, the breast cancer patients were divided into high-expressed subgroups and low-expressed subgroups." (PMID 36090993, 2022). "A2M-AS1 increases breast cancer cell invasion and migration by regulating the cell adhesion molecules CD2 and SELL; therefore, our findings provide a potential prognostic biomarker and therapeutic target for breast cancer." (PMID 32352014, 2020). "In summary, A2M-AS1, by regulating the expression of CD2 and SELL, promotes invasion and migration in breast cancer." (PMID 32352014, 2020). "In HR−/HER2+ breast cancer, four genes (three i-genes BTN3A2, CD2, and TRBC1 and the p-gene MMP11) were significantly associated with distant metastasis-free survival (DMFS)." (PMID 28409241, 2017).
breast carcinoma (continued). "In HR−/HER2+ breast cancer, MMP11 (hazard ratio 1.49; 95% CI 1.08–2.04; P = 0.014) and CD2 (hazard ratio 0.66; 95% CI 0.47–0.94; P = 0.022) retained their statistical significance for DMFS in multivariate analysis." (PMID 28409241, 2017). "We also examined the relationship between MMP11 and CD2 gene expression and prognosis of patients with HR−/HER2+ breast cancer using public dataset to confirm their clinical significance in other cohorts." (PMID 28409241, 2017). "The findings suggest that CD2 enhances CTL function against tumor cells and influences their metabolic states, highlighting the role of CD2 in remodeling the brain metastatic microenvironment in breast cancer." (PMID 40859981, 2025). "Furthermore, reduced CD2 expression weakened CTL‐mediated recognition and induction of apoptosis in breast cancer cells while promoting tumor proliferation and migration." (PMID 40859981, 2025). "For instance, A2M-AS1 has been reported to have regulatory effects on downstream factors such as CD2 and SELL, in the cell adhesion molecule pathway, indicating that A2M-AS1 may be a visible candidate prognostic factor and therapeutic target for breast cancer." (PMID 35237359, 2022). "A recent study also discovered that increased expression of immune response-related genes, BTN3A2, CD2, and TRBC1 was correlated with favorable prognosis of HR−/HER2+ breast cancer, indicating the importance of immune response-related genes in predicting the treatment outcome for this subtype." (PMID 33435254, 2021). "Functional experiments showed that A2M-AS1 enhances breast cancer cell proliferation, invasion, and migration, and bioinformatics analysis showed that A2M-AS1 potentially regulates cell adhesion molecule pathway members, including CD2, CD8A, and SELL." (PMID 32352014, 2020). "Importantly, we found that the gene expression of MMP11 and CD2 are independent prognostic factors for DMFS in HR−/HER2+ breast cancer, whereas clinical variables were not significant prognostic indicators." (PMID 28409241, 2017). "Additionally, bioinformatics analysis of genes coexpressed with A2M-AS1 in the context of human breast cancer combined with qRT-PCR and Western blot assays revealed that A2M-AS1 exerts regulatory effects on downstream factors in the cell adhesion molecule pathway, including CD2 and SELL." (PMID 32352014, 2020). "In addition, elevated expression of i-genes (BTN3A2, CD2, and TRBC1) was significantly correlated with favorable clinical outcome in HR−/HER2+ breast cancer, but not in other subtypes." (PMID 28409241, 2017).
T-cell lymphoma (17 papers, 2009 to 2025). "Defects in CD58 (either loss of expression or mutations) have been reported in B cell and T cell lymphomas (63, –65), and CD2 expression on tumor-infiltrating T cells has been shown to correlate with their function in several cancers." (PMID 36598945, 2023). "The key diagnostic features of NK/T cell lymphoma are the demonstration of NK/T cell markers (CD2, cytoplasmic CD3, CD56, and cytotoxic granule proteins) and Epstein-Barr virus (EBV), which is uniformly present." (PMID 23217032, 2012). "Typical NK/T-cell lymphomas are characterized by a specific T-immunophenotype with immunohistochemical features that include positive staining for CD2, CD56, and cytoplasmic CD3ε, whereas surface CD3 is usually negative." (PMID 40438688, 2025). "For NK/T-cell lymphomas, markers like CD2, cytoplasmic CD3, CD56, and cytotoxic granules (granzyme B, perforin, TIA-1) are typically positive." (PMID 41367858, 2025). "Anaplastic large cell lymphoma is a CD30+ T-cell lymphoma, usually positive for CD2, CD4, and variable expression of CD5, CD7, and CD8 but negative for B-cell markers." (PMID 37958219, 2023). "This tumor is a CD30+ T-cell lymphoma that is usually positive for CD2 and CD4 with variable expression of CD5, CD7, and CD8 but it is negative for EBER." (PMID 37958219, 2023). "Because the CD2/CD58 interaction stabilizes the HRS/T synapses, monoclonal anti-CD2 antibodies, already in clinical trials for T-cell lymphomas and autoimmune conditions, may counter rosette formation and prove of some benefit in cHL." (PMID 33327433, 2020). "The characteristic immunophenotype of NK/T-cell lymphoma is CD56+, CD2+, surface CD3-, LCA+." (PMID 28874193, 2017). "Previous studies of Myc-induced CD4+/CD8+ T–cell lymphoma in the CD2-MYC model in a lpr genetic background showed that deletion of Fas did not accelerate T-cell lymphoma development, although an increased population of CD4+ T-cells was found." (PMID 22393362, 2012). "The CD2, CD3, CD4, CD7 and CD8 are used to determine the T cell lymphoma." (PMID 20062547, 2009). "Most mature T-cell lymphomas in our cohort were CD4-positive and were characterised by abnormal immunophenotypic features, including an altered expression of antigens of the T-cell lineage (e.g., CD2, CD3, CD5, and CD7), and abnormal expression of additional antigens such as CD279 and CD10." (PMID 39796028, 2024).
autoimmune disease (12 papers, 2007 to 2025). A disorder resulting from loss of function or tissue destruction of an organ or multiple organs, arising from humoral or cellular immune responses of the individual to their own tissue constituents. "Hormonal-mediated regulation of CD2 is a conserved mechanism that has implications for the sexual dimorphism in the susceptibility to -and treatment of- autoimmune diseases like RA." (PMID 34552089, 2021). "The CD2/CD58/CD48 pathway is associated with the human autoimmune diseases multiple sclerosis and rheumatoid arthritis and with a model of murine lupus." (PMID 26438525, 2015). "Moreover, the CD2/CD58 pathway is associated with the human autoimmune diseases, multiple sclerosis, and rheumatoid arthritis, and the CD2/CD48 pathway is associated with a model of murine lupus." (PMID 26438525, 2015). "Here the authors show this locus houses a non-coding polymorphic estrogen receptor binding site and how it regulates neighbouring gene expression of CD2, implicating CD2 signalling in the sexual dimorphism of a variety of T cell-dependent autoimmune diseases." (PMID 34552089, 2021). "We find that E2-mediated regulation of Cd2 is a conserved mechanism that influences T cell activation in a sex-specific manner, contributing to the sexual dimorphism in autoimmune diseases." (PMID 34552089, 2021). "Alefacept (anti-CD2) biological therapy selectively targets effector memory T cells (Tem) in psoriasis vulgaris, a model Type 1 autoimmune disease." (PMID 17555598, 2007). "Importantly, we find oestrogen regulation of CD2 expression to be a conserved mechanism in humans likely contributing to the sexual dimorphism in T cell-mediated autoimmune diseases." (PMID 34552089, 2021). "The increased proportion of CD5high cells among Egr2/3−/− MP CD4 T cells, and auto-reactive T cells and autoimmune disease in CD2-Egr2/3−/− mice suggests that these enriched clones may have high affinity for self-antigen." (PMID 32709717, 2020). "Previous studies have demonstrated that soluble CD58 can block the interaction of CD2/CD58, thereby playing a therapeutic role in inflammation and autoimmune diseases." (PMID 38550602, 2024). "CD2 and CD58 molecules have been shown to be important in inflammatory and autoimmune diseases such as rheumatoid arthritis (RA)." (PMID 26111183, 2015).
viral infection (11 papers, 2011 to 2025). "CD8 and CD2 signatures on CSF EVPs from diseases linked with viruses were reproducibly shown to be elevated in comparison to non-viral diseases and controls, potentially indicating an EVP signature of viral-mediated disease in the CNS." (PMID 37622115, 2023). "Consistent with CD2-Egr2/3−/− mice, Egr2- and Egr3-deficient T cells in the chimeras displayed impaired expansion and enhanced differentiation in response to viral infection." (PMID 28487311, 2017). "Germinal center formation was defective in CD2‐Egr2/3−/− mice in response to viral infection, consistent with our previous findings." (PMID 39568245, 2025). "As a co-stimulatory molecule, CD2 enhances T cell responses, which is critical for alleviating viral infections such as COVID-19." (PMID 41332907, 2025). "Tfh cell development and function is impaired in CD2‐Egr2/3−/− mice, and these mice fail to generate germinal centers in response to viral infection." (PMID 39568245, 2025). "Following viral infection, CD2-Egr2−/−Egr3−/− mice displayed more severe clinical signs than wild type counterparts, and viral load in the lungs of CD2-Egr2−/−Egr3−/− mice was much higher than that in wild type counterparts." (PMID 25979336, 2015). "We discovered that the differentiation of Tfh cells in response to virus infection was defective in CD2-Egr2−/−Egr3−/− mice compared with wild type counterparts." (PMID 25979336, 2015). "Another CD16A mutation, leading to deficient CD2 expression and natural cytotoxicity but unaltered ADCC, was associated to different viral infections, including EBV in some patients, in line with the role of direct NK cell recognition in viral infection control." (PMID 34415956, 2021). "However, the CD2+CD8α+ γδ T subpopulation was increased in all three viral infections with the greatest increase seen in PRRSV infection." (PMID 25186625, 2014). "In response to virus infection, CD44highGFP-Egr2high and CD44highGFP-Egr2low T cells produced IL2 and effector cytokines differentially, again similar to T cells from CD2-Egr2 transgenic and CD2-Egr2/3−/− mice." (PMID 28487311, 2017). "We found that the differentiation of Tfh cells in CD2-Egr2−/−Egr3−/−mice, which lack EGR2 and -3 in B and T cells, was severely defective, resulting in failure to form GCs after virus infection." (PMID 25979336, 2015). "Following virus infection, most of the Tfh cells in wild type mice expressed BCL6, whereas BCL6 expression was defective in the few remaining Tfh cells in CD2-Egr2−/−Egr3−/− mice." (PMID 25979336, 2015). "T-bet expression was not defective in CD4 and CD8 T cells from CD2-specific Egr2/3−/− mice in response to virus infection; indeed, T-bet+ CD4 T cells were higher in CD2-specific Egr2/3−/− mice." (PMID 28455436, 2017). "Thus, the up- and down-regulated gene profiles were consistent with the defects in T cells observed in CD2-Egr2/3−/− mice and the functions of Egr2high and Egr2low T cells from GFP-Egr2 knock-in mice in response to viral infection." (PMID 28487311, 2017). "The proportions of effector CD2+CD21— and resting CD2—CD21— AFC/PC (data not shown) in the MLN remained unchanged in all three viral infections." (PMID 25186625, 2014). "However, HIV latent infection of resting T cells were highly diminished by CD2 prestimulation, suggesting that the residual viral particles entering cells did not contribute to the productive viral infection process." (PMID 34765923, 2021). "However, virus infection did not induce GC formation in CD2-Egr2−/−Egr3−/− mice, and the development of GC B cells was severely impaired." (PMID 25979336, 2015). "Furthermore, CD8+ (p < 0.0001), CD2+ (p < 0.0001), CD44+ (p = 0.0176), and CD40+ (p = 0.0413) EVP signals were significantly increased in the CSF from individuals with viral infections compared to those without." (PMID 37622115, 2023).
melanoma (10 papers, 2006 to 2025). A malignant, usually aggressive tumor composed of atypical, neoplastic melanocytes. "Immune response molecules, namely CD2 and PD-L1, were chosen in our study to define immune-type melanomas, which have been associated with improved patients’ survival." (PMID 33003444, 2020). "Notably, NRAS-mutated melanomas in our study were related to lower CD2 expression levels." (PMID 33003444, 2020). "Over the entire cohort, melanoma-specific survival (MSS) was influenced by CD2, PDL1 (CD274), and MITF (p = 0.01, p = 0.003, p = 0.03, respectively)." (PMID 33003444, 2020). "While it was not possible to detect PRAME-specific responses against the K562 HLA-A2+ cells or the 518A2 melanoma cells using the standard reporter, the CD2+CD226+ J76 PRAME TPR were stimulated by endogenously processed PRAME antigen expressed by these cells." (PMID 29707134, 2018). "Moreover, a DC signature (CD14+CD2+LY75+) associated with stromal macrophages linked with antigen capture and presentation was found associated with long-term survival of melanoma patients." (PMID 37190135, 2023). "Interestingly, by performing spatially resolved transcriptomic analysis of CD14+ cells from different localization in melanoma tumor sections, the group of K. Palucka identified a DC signature (CD14+CD2+LY75+) in the stroma linked with antigen capture and presentation." (PMID 37190135, 2023). "Hence, combining melanoma antigen-specific TCRs with CD2::CD28 chimeric receptors might have potential in adoptive T cell therapy, since melanoma cells were shown to have high expression of CD58." (PMID 29707134, 2018). "CD2, CD8, and CD53 are mentioned together in a leukocyte infiltration score predicting melanoma patient prognosis." (PMID 38397409, 2024). "The markers utilized in the conducted study, as defined by Tirosh and colleagues, successfully differentiated between various cell types, including melanoma cell (MLANA, PMEL), T cell (CD2, CD3D, CD3E, CD4, CD8A)." (PMID 37620327, 2023). "We found that CD58 and CD155, which function as binding partners for the adhesion molecules CD2 and CD226, respectively, are broadly expressed in cell lines derived from human melanomas or B cell tumors." (PMID 29707134, 2018).
myeloma (10 papers, 2012 to 2025). "We are currently investigating myeloma subtypes and have obtained preliminary results for the CD-2 genetic subtype." (PMID 40565478, 2025). "In contrast, the low-risk group showed enrichment for downregulated multiple myeloma (MM) pathways, upregulated MM CD1 and CD2 pathways, and downregulated MM C cluster pathways." (PMID 41040512, 2025). "A clinical study (NCT00938626) targeting myeloma precursor cells in standard and high-risk MM patients administered the patients with anti-CD3 × anti-CD2 BsAb-armed activated T cell infusions prior to autoSCT." (PMID 32391000, 2020). "We further correlated DAZAP2 expression with normal plasma cells and malignant myeloma cells, as well as the molecular subtypes which the dataset includes 8 genetic subtypes (MY, PR, LB, MS, HP, CD-1, CD-2, and MF) from 351 newly diagnosed myeloma cases." (PMID 22792345, 2012).